CXCR4 (C-X-C motif chemokine receptor 4)
Diseases named in the same sentence as CXCR4 in open-access papers (continued):
Sharing a sentence is not in itself a finding about the gene and the disease.
adenoma (continued). "Finally, CXCR4 is an easily druggable target and the characterization of its role in pituitary adenomas could pave the way for novel pharmacological approaches, especially for those adenoma subtypes, (i.e., TSH and ACTH secreting tumors, as well as NFPA) still waiting for efficacious drugs." (PMID 25484899, 2014). "The C-X-C chemokine receptor type 4 (CXCR4) is a transmembrane G protein-coupled receptor; the expression of this protein has been reported to be upregulated in aldosterone-producing tissue but is almost negligible in non-functional adenoma(NFA)." (PMID 38419957, 2024). "Therefore, the better characterization of CXCR4/ACKR3/CXCL12 axis in PAs could pave the way for novel pharmacological approaches, especially for those adenoma subtypes (i.e., TSH and ACTH-secreting tumors, as well as NFPA) still waiting for efficacious therapeutic drugs." (PMID 26441831, 2015). "Normal mammary gland tissue did not express detectable level of CXCR4, while epithelial cells of basaloid adenoma appeared weakly positive for CXCR4 (CXCR4 score 1+) in scattered areas throughout the section, and the complex adenoma was essentially negative (CXCR4 score 0)." (PMID 22417013, 2012). "The PET tracer 68Ga-Pentixafor targets CXC chemokine receptor type 4 (CXCR4), a transmembrane G protein-coupled receptor with significantly higher expression in aldosterone-producing adenomas (APA) than in normal adrenal tissue and nonfunctional adenomas." (PMID 40246740, 2025). "Given that previous studies have reported a negative correlation between adenoma size and CYP11B2 expression and a positive correlation between the expression level of CXCR4 and CYP11B2, the expression density of CXCR4 in micro-APA should theoretically be higher than that in macro-APA." (PMID 40084145, 2025). "The staining of CXCL12, CXCR4, and FAPα was more intense in high-grade dysplastic epithelial cells and intramucosal invasive LARC cells than in the non-neoplastic epithelial cells of the 16 adenoma cases (p < 0.001 for each)." (PMID 34976180, 2022). "Heinze et al16 found that the expression of CXCR4 was increased in patients with APA compared with those with normal adrenal tissue and those with nonfunctioning adenoma, but whether the expression of CXCR4 was increased in hyperplastic adrenal tissue in patients with PA was unknown." (PMID 36795418, 2023). "In contrast to previous studies, these human adenoma cells failed to expand when xenografted into SCID mice; however, they could identify a similar side population in the AtT20 pituitary tumour cell line, which expressed SOX2 and CXCR4, and can form de novo tumours in xenograft transplantations." (PMID 28855316, 2018).
Arthritis (16 papers, 2009 to 2026). Inflammation of a joint. "Cxcr4-deficient mice developed arthritis with very low incidence (two of 11), but the severity of arthritis was comparable to that of control mice." (PMID 20939892, 2010). "A significant improvement in arthritis pathology was demonstrated by low-dose MTX-mediated downregulation of CXCR4." (PMID 39070795, 2024). "The CXCL12/CXCR4 axis is therefore a promising drug target in RA, and treatment of mice with collagen-induced arthritis with the CXCR4-specific antagonist AMD3100 was shown to reduce disease severity." (PMID 31572390, 2019). "Among analyzed chemokine receptors, the DP subset expressing CXCR4 showed the most significant associations with inflammatory indicators and disease activity, including TNF-α concentration, duration of arthritis, autoantibody levels, and bone resorption." (PMID 28619088, 2017). "DBA/1J mice were immunized with IIC/CFA to induce arthritis, and the expression of CXCR4 was determined with FACS analysis." (PMID 20939892, 2010). "Of interest was their finding that expression of CXCR4 was unexpectedly high among all arthritis subjects." (PMID 19555476, 2009). "Additionally, other studies have shown that the expression of CCR1, CCR2, CCR4, CCR5, and CXCR4 on the surface of B cells in synovial fluid (SF) of arthritis patients is significantly increased." (PMID 41481752, 2026). "Furthermore, we showed that CCR6, which is important for the development of arthritis in SKG mice by enhancing the migration of Th17 cells, was expressed normally in Cxcr4-deficient T cells." (PMID 20939892, 2010). "They postulated that decreased circulating soluble DPPIV/CD26 levels in arthritis may influence DPPIV/CD26-mediated regulation of the chemotactic SDF-1/CXCR4 axis." (PMID 20520837, 2010). "The importance of CXCR4 expression in synovial membrane inflammation has been emphasised by the inhibition of collagen-induced arthritis by the CXCR4 antagonist T140, and by the finding of elevated CXCR4 gene expression in RA synovial biopsies with follicular-like lymphoid structures." (PMID 19500335, 2009). "B cells from the SF of arthritis patients showed a significant increase in the surface expression of CCR1, CCR2, CCR4, CCR5 and CXCR4 with respect to PB." (PMID 29880013, 2018). "Therefore, once inflammation starts, other chemokines and cytokines may play more important roles than CXCR4, or other chemokines may substitute for the role of CXCR4 in the later stages of inflammation, resulting in the development of arthritis in Cxcr4flox/flox/Lck-Cre mice." (PMID 20939892, 2010). "OCPs from patients with arthritis had higher expression of CCR1, CCR2, CCR4, CXCR3, and CXCR4." (PMID 28619088, 2017). "The expression of CXCR4 increased in mice immunized with CFA only, but LN cells from these mice did not respond to stimulation by IIC or develop arthritis." (PMID 20939892, 2010). "Although immunization with CFA without IIC enhanced CXCR4 expression in T cells, this could not induce arthritis, suggesting that CXCR4 expression in IIC-specific T cells is important for the induction of arthritis." (PMID 20939892, 2010).
bladder cancer (16 papers, 2008 to 2024). "In the present study, we found that overexpression of RON and CXCR4 was positively associated with the aggressive behaviors in bladder cancer, which supports the hypothesis that RON related signaling pathways play a vital role in bladder cancer invasion and metastasis." (PMID 36103228, 2022). "CXCR4 is expressed by normal urothelium and may be associated with bladder cancer." (PMID 19066630, 2008). "Our results are consistent with previous findings on the significance of RON and CXCR4 in bladder cancer." (PMID 36103228, 2022). "The purpose of this study is to reveal intrinsic the relationship between RON and CXCR4 and their roles in regulating bladder cancer migration and invasion." (PMID 36103228, 2022). "SDF-1 is a ligand for the chemokine receptors CXCR4 and CXCR7 and induces proliferation of bladder cancer cells via the activation of CXCR4." (PMID 33889301, 2021). "One study demonstrated high levels of CXCR4 expression in invasive and locally advanced bladder cancer tissue samples, low levels in superficial bladder tumor cells, and no expression in normal urothelial cells." (PMID 19719844, 2009). "Exposure of bladder cancer cells expressing CXCR4 to CXCL12 (the cytokine known as stromal cell-derived factor-1) leads to cell migration and invasion of the extracellular matrix." (PMID 19719844, 2009). "CXCR4 has also recently been found to participate in the process of metastases of several human tumors, including bladder cancer." (PMID 19719844, 2009). "CXCR4 mRNA expression in normal human urothelium, bladder cancer and also bladder cancer cell lines (J82 and T24) was previously reported." (PMID 19066630, 2008). "Relationship between the expression of CXCR4 and clinical pathological features of bladder cancer." (PMID 36103228, 2022). "The CXCR4/CXCL12 axis appears crucial in the metastasis of bladder cancer." (PMID 19719844, 2009). "Therefore, we speculated that CD164 possibly played roles in bladder cancer through regulating the expression of CXCR4 and relevant pathways." (PMID 30022623, 2018). "Of them, CXCR4 and IL6 had long been thought to be oncogenes in bladder cancer which promoted various tumor behaviors." (PMID 36263004, 2022). "CXCL12 and CXCR4 are not expressed in normal bladder tissue, but exhibit highly expression in bladder carcinomas." (PMID 39606239, 2024). "The cancer tissues with higher levels of RON expression also tended to have higher CXCR4 expression, indicating that high CXCR4 expression might be related to RON expression in the pathogenesis of bladder cancer." (PMID 36103228, 2022). "TSA is known to upregulate chemokine receptors, such as CXCR4, and increase CAR expression on bladder cancer cells although its effects on MSCs are unknown." (PMID 34068264, 2021).
chondrosarcoma (16 papers, 2010 to 2024). A malignant cartilaginous matrix-producing mesenchymal neoplasm arising from the bone and soft tissue. "Hypoxia increases CXCR4 expression in both ES and chondrosarcoma cell lines grown in vitro or as tumours in vivo in nude mice." (PMID 29098360, 2018). "The CXCR4 ligand SDF-1α doubled secreted VEGFA under hypoxic conditions in human chondrosarcoma cell line and these effects were inhibited by CXCR4 siRNA." (PMID 24647809, 2014). "It has also been observed that the expression of CXCR4 in human chondrosarcoma tissues and chondrosarcoma cell lines is higher than in normal cartilage and in human chondrocytes." (PMID 24490159, 2013). "In chondrosarcoma of bone, CXCR4 showed higher immunohistochemical staining in high-grade than in low-grade samples, being a potential marker of aggressiveness." (PMID 22518090, 2012). "CXCR4 and CXCL12 expressions have been found to be increased in both chondrosarcoma tissue and cell lines, with the expression of CXCR4 correlating with tumor grade." (PMID 21234386, 2011). "We have shown that one mechanism of increased MMP1 in chondrosarcoma is mediated through CXCR4 signaling, which is amplified by hypoxia, and is mediated by ERK, but not other MAP kinases." (PMID 20102637, 2010). "As a first step in evaluating the potential role of SDF1 and CXCR4 in chondrosarcoma biology, we analyzed primary chondrosarcoma tissue and articular cartilage for expression of mRNA and protein for these genes using qRT-PCR and Western blotting." (PMID 20102637, 2010). "We present data that shows hypoxia mediated increase in MMP1 expression and chondrosarcoma invasion is partially mediated by CXCR4 signaling." (PMID 20102637, 2010). "Chondrosarcoma cell invasion is increased by hypoxia induced expression of CXCR4 and MMP1 and is mediated by HIF-1a and ERK." (PMID 20102637, 2010). "In other tumors and chondrosarcoma, CXCR4 signaling upregulates other MMPs such as MMP-2, 8 and -9 and -13." (PMID 20102637, 2010). "CXCR4 and its ligand, SDF1, are upregulated in primary chondrosarcoma tumors compared to normal articular cartilage, and CXCR4 was upregulated in chondrosarcoma cell line JJ compared to normal chondrocytes." (PMID 20102637, 2010). "Likewise, chondrosarcoma cells exposed to 2% oxygen for 48 h showed a C-X-C chemokine receptor type 4 (CXCR4) overexpression, which augmented MMP-1 transcription." (PMID 38069210, 2023). "Finally, in a mouse model of chondrosarcoma, siRNA inhibition of CXCR4 decreased overall tumour volume and incidence of metastases to the lungs." (PMID 29098360, 2018). "Interestingly, the CXCL12/SDF-1 chemokine, which is constitutively secreted by human lung epithelium cells, has been shown to enhance the invasiveness of chondrosarcoma cells by increasing αvβ3 integrin expression, through the CXCR4/ERK/NF-κB pathway." (PMID 24490159, 2013). "CXCR4 blockade can inhibit the effects of hypoxia on MMP1 expression and chondrosarcoma invasion in vitro, suggesting that CXCR4 blockade could be a therapeutic target to inhibit chondrosarcoma invasion and metastasis." (PMID 20102637, 2010). "Our results show that HIF-1a also upregulates CXCR4 in chondrosarcoma." (PMID 20102637, 2010). "Both invasion and MMP1 can be inhibited with CXCR4 blockade, suggesting that CXCR4/SDF1 signaling may be a therapeutic target for chondrosarcoma." (PMID 20102637, 2010). "Thus, the authors suggest the CXCR4/SDF1 signaling as a therapeutic target for chondrosarcoma." (PMID 28439237, 2017). "CXCR4 signaling regulates the expression of matrix metalloproteinase 1 (MMP1), a marker of chondrosarcoma tissue invasion, metastasis, and poor prognosis." (PMID 21234386, 2011). "This study provides the first indication that CXCR4 is regulated by hypoxia and specifically HIF-1a in chondrosarcoma cells." (PMID 20102637, 2010).
chondrosarcoma (continued). "We also show that increased CXCR4 signaling regulates expression of MMP1, a factor known to be involved with chondrosarcoma metastasis and a marker for poor prognosis." (PMID 20102637, 2010). "siRNA directed against HIF-1a, CXCR4, ERK; CXCR4 blockade with AMD3100; or ERK inhibitor U0126 all efficiently inhibited the increase in invasion of chondrosarcoma cells during hypoxia." (PMID 20102637, 2010). "Hypoxia and specifically HIF-1a increased CXCR4 and MMP1 expression in JJ cell line and chondrosarcoma invasion in vitro." (PMID 20102637, 2010). "The present study determined the effect of hypoxia and specifically HIF-1a on expression of CXCR4 and MMP1 and their role in chondrosarcoma cell invasion." (PMID 20102637, 2010). "Interestingly, chondrosarcoma cell invasion is increased by hypoxia-induced expression of CXCR4 and MMP1, a process mediated by HIF1α and ERK, and CXCL12, also called SDF-1, increases the invasiveness of chondrosarcoma cells." (PMID 21647363, 2011). "However, this project is the first to link the combined effects of HIF-1a on CXCR4 and MMP1 expression and the indirect effect of HIF-1a on MMP1 expression acting through CXCR4, which independently increases MMP1 in chondrosarcoma cells." (PMID 20102637, 2010). "The hypoxia mediated increase in MMP1 expression and chondrosarcoma invasion could be inhibited by siRNA directed at HIF-1a or CXCR4, the CXCR4 inhibitor AMD3100, as well as with ERK inhibitor U0126 and ERK siRNA." (PMID 20102637, 2010).
fibrosis (16 papers, 2012 to 2025). the formation of excess fibrous connective tissue in an organ or tissue in a reparative or reactive process. "The development of dual-functioning nanoparticles for the effective delivery of antifibrotic RNA together with a CXCR4 inhibitor thus promises to improve the treatment of AALD fibrosis." (PMID 35336043, 2022). "The promoting effect of CXCL12 on ICT during development is consistent with the recognized role of CXCL12/CXCR4 axis in adult fibrosis." (PMID 29222527, 2017). "The proportion of mild fibrosis patients infected with CXCR4-using viruses (n = 23, 31%) was similar to that of the severe fibrosis patients (n = 27, 28%, p = 0.6)." (PMID 23226258, 2012). "In this study, we tested the surface CXCR4 expression on the MSCs treated by microbubble-mediated ultrasound irradiation and counted the number of homing MSCs labeled by green fluorescent protein in the fibrosis liver of mice." (PMID 38402155, 2024). "However, by 6-months of age, CXCR4 cKO hearts revealed significant cardiac myocyte hypertrophy, the presence of cellular infiltrates, and progressive interstitial/peri-vascular fibrosis as compared with age-matched wild-type controls." (PMID 31071921, 2019). "In accordance with previous studies, we observed increased CXCR4 expression, decreased Ly6G expression, and reduced cell size and granularity on aged neutrophils from both fibrotic and nonfibrotic mice, validating our method of distinguishing neutrophil age in the bleomycin model of fibrosis." (PMID 36534439, 2022). "Experimental validation in a bleomycin-induced fibrosis model confirmed the upregulation of GRGs (such as AURKA, CXCR4)." (PMID 40093327, 2025). "The hepatic gene expression of CXCR4 increased almost 2.5-fold, and miR-155 was also elevated around 3-fold in the AALD fibrosis group (EtOH/CCl4)." (PMID 35336043, 2022). "In contrast to CXCR4, miR-155 proved to be a valid therapeutic target in AALD fibrosis." (PMID 35336043, 2022). "CXCR4, the receptor for CXCL12, a chemokine expressed by inflamed biliary epithelium in primary biliary cirrhosis and HCV, was enriched in portal compared to parenchymal regions in HCV patients with advanced fibrosis." (PMID 27309850, 2016). "To determine whether SDF-1α/CXCR4 axis also regulates the recruitment of MSCs in fibrotic liver, we measured the expression level of SDF-1α in liver and BM in CCl4-induced fibrosis model with the time going." (PMID 26643997, 2015).
Hyperglycemia (16 papers, 2010 to 2026). An increased concentration of glucose in the blood. "The decrease in the CXCR4 expression by long-term exposure to hyperglycemia induces damage to CM cells." (PMID 34639171, 2021). "SDF-1 improves the mobilization, migration, homing, and vasculogenesis of EPCs under hyperglycemia via activating the SDF-1/CXCR4 axis." (PMID 32714394, 2020). "T3M4 cells exposed directly to hyperglycemia or to different conditioned PSC culture media expressed increased amount of CXCR4, mostly after treatment of T3M4 cells with the culture medium of PSCs that were previously exposed to CHG." (PMID 26010611, 2015). "In cancer cells, hyperglycemia induced an increased expression of CXCR4, a CXCL12 receptor that was also induced by PSC’s conditioned medium." (PMID 26010611, 2015). "Our in vitro data showed that HG down-regulated CXCR4 expression in EPCs, suggesting that hyperglycemia per se can impair the SDF-1α/CXCR4 axis." (PMID 23185548, 2012). "However, hyperglycaemia causes a partial loss of SDF‐1activity, which is then unable to bind to CXCR4 or inhibit the dedifferentiation of pancreatic β cells." (PMID 34935260, 2022). "Earlier studies have shown that hyperglycemia could increase the expression of CXCR4 and also that CXCR4 inhibitor could reduce myocardial fibrosis in Type 1 diabetic animals." (PMID 33924458, 2021). "This suggests that hyperglycemia mediated changes in CXCR4 could be involved in TGF-β induced cardiac remodeling." (PMID 33924458, 2021). "Our in vitro studies with AC-16 cardiomyocytes demonstrated that CXCR4 antagonist AMD3100 could block the hyperglycemia mediated increase in TGFβ similar to the GLC mediated reduction." (PMID 33924458, 2021). "Therefore, it deserves further investigation on if other factors besides hyperglycemia can also lead to the impairment of SDF-1α/CXCR4." (PMID 23185548, 2012). "AC16 cardiomyocyte cells were also treated overnight with 25 mM of glucose and hyperglycemia cells were treated with AMD3100 (CXCR4 antagonist) to estimate the connection between TGF-β and CXCR4 pathways." (PMID 34512937, 2021). "Our findings of hyperglycemia, hyperinsulinemia, hyperleptinemia, the circulating number of WBC, neutrophils, and lymphocytes, plasma TGF-β1, along with tumor CD45, SDF-1α, and CXCR4 in obese mice, were consistent with the reported studies." (PMID 32121098, 2020). "Hyperglycemia induces increased CXCL12 production by the PSCs, and its receptor, CXCR4 on cancer cells." (PMID 26010611, 2015). "Whilst the authors demonstrated that this was due to the increased expression of SDF-1α, Pim-1 has been shown to positively regulate CXCR4 signalling in other cell types, indicating the potential to target the kinase to prevent CXCR4-mediated VSMC proliferation during hyperglycaemia." (PMID 37511341, 2023). "We further examined that hyperglycemia mediated the decrease in the gap junction protein CX43, as well as CXC chemokine receptor CXCR4 which may affect the physiological functions of the cardiomyocytes when exposed to high glucose for 24 and 48 h." (PMID 34639171, 2021). "Moreover, superoxide induced by hyperglycemia may destabilize HIF-1α and reduce the activation of SDF-1α, VEGF and CXCR4 in response to hypoxia." (PMID 26305217, 2015).